BRCA1 (BRCA1 DNA repair associated)
Diseases named in the same sentence as BRCA1 in open-access papers (continued):
Sharing a sentence is not in itself a finding about the gene and the disease.
breast cancer (continued). "Prospective studies could not confirm a risk reduction for breast cancer especially in BRCA1 mutation carriers." (PMID 33885953, 2021). "Although BRCAm carriers are more likely to have a poor response to ovarian stimulation, Grynberg at al. have recently shown that BRCA1/2 pathogenic variants do not seem to affect the capacity of oocytes to mature in vitro in breast cancer patients candidate for fertility preservation." (PMID 34627117, 2021). "Indeed, several studies reported higher levels of proteins or biomarkers associated with elevated thrombotic risk in patients with BRCA1/2 mutations compared to controls with no mutations, independent of breast cancer." (PMID 34154667, 2021). "The analytic model was based on analyses of the effects of HRT among women with a family history of breast cancer, not specifically on BRCA1/2 mutation carriers, where HRT might have a different effect." (PMID 33885953, 2021). "Additionally, the downregulation of BRCA1 repressed breast cancer cell growth." (PMID 33888730, 2021). "BRCA1/2 mutation carriers may have been treated for breast cancer, which can be cardiotoxic and potentially have a negative impact on the brain." (PMID 33480862, 2021). "In breast cancer, UBE2T was shown to facilitate the polyubiquitination and degradation of BRCA1—an E3 ubiquitin ligase and a critical tumor suppressor gene in hereditary breast cancer--by interacting with the BRCA1/BRCA1-associated RING domain protein (BARD1) complex." (PMID 34257599, 2021). "Identification of disease-associated genetic changes in breast cancer susceptibility genes, including BRCA1, BRCA2 and PALB2, not only has actionable implications for carriers, but also for the additional members of their family who are found to carry the high-risk variant." (PMID 33113089, 2021). "In the present study, we attempted to determine the prevalence of pathogenic or likely pathogenic variants of BRCA1 or BRCA2 among the selected group of patients with breast cancer (not diagnosed as mutation carriers with the standard screening procedure in 2003–2015)." (PMID 33918338, 2021). "Interestingly, sodium arsenite exposure was shown to increase Brca1 promoter methylation in the human breast cancer cell line MCF7 in vitro, supporting that it may be a useful marker." (PMID 34681626, 2021). "Mutation in the BRCA1/2 gene increases the risk of breast cancer in men but not in females." (PMID 35036180, 2021). "Indeed, ovarian and breast cancer patients without BRCA1/2 mutations demonstrate positive, yet variable, clinical responses to therapeutic agents that target HRD." (PMID 34711195, 2021). "Although BRCA1-associated mammary tumors are known as triple-negative breast cancers, histopathological analysis of BRCA1-associated breast cancer showed that 32.7% and 22.5% of breast cancer from BRCA1 carrier were not triple-negative and ERα-positive, respectively." (PMID 33767581, 2021). "Similarly, the BRACness phenotype, which is defined as any defect that impacts HR repair and phenocopies the mutation or loss BRCA1/2, is also strongly linked with sensitivity to platinum and PARP inhibitors, especially in ovarian and breast cancer." (PMID 32457904, 2020). "In the present study, we determined the contribution of pathogenic RECQL variants to hereditary breast cancer in 302 early-onset and familial BRCA1 and BRCA2 negative patients with ER positive and/or PR positive breast cancer in a South Asian population from Pakistan." (PMID 33342430, 2020). "In addition, miR-182 downregulation could desensitize BRCA1-proficient breast cancer cells to PARPis." (PMID 32122376, 2020). "Indeed, BRCA1/2 mutant cancers are selectively killed by PARP inhibitors, which has led to the approval of these agents to treat HR-deficient ovarian and breast cancers." (PMID 32295316, 2020). "Breast cancer with BRCA1 (but not BRCA2) mutations is known to typically have a basal phenotype." (PMID 32766142, 2020).
breast cancer (continued). "This emphasizes our rationale of the impact that breast surgery can have on a woman’s sexual health, which is in line with our previous publication also showing low ‘Q-sexual well-being’ scores in surgical treated breast cancer patients (without a BRCA1/2 mutation)." (PMID 31832891, 2020). "In one study, women at increased risk for breast cancer based on family history who received negative results via current BRCA1/2 testing often misconceived that results either meant nothing, or that their risk for developing breast cancer was as low as that of the average woman." (PMID 32316380, 2020). "Controlled ovarian stimulation seems to be safe and does not increase the baseline risk of neither ovarian nor breast cancer in patients harbouring BRCA1/2 mutations, especially when utilising stimulation protocols which uses letrozole to maintain physiological levels of oestrogen." (PMID 32419845, 2020). "The somatic BRCA1 mutations are not screened in breast cancer with unrecognized familial history, but they are estimated as being rather frequent in early and old onset patients of breast cancer." (PMID 32882966, 2020). "In terms of histology and transcription profile these cancers have similarities to BRCA-1-linked breast cancers, and it is hypothesized that BRCA1 pathway is non-functional in this type of breast cancer." (PMID 32245065, 2020). "Besides BRCA1 and BRCA2, more than 100 loci are known to be associated with breast cancer risk." (PMID 33240314, 2020). "In a subsequent study, 206 women with BRCA1 or−2 mutations had serum OPG levels measured, were divided into low OPG (mean 62.9 pg/ml; range 4.2–94.5 pg/ml) or high OPG (mean 168.1 pg/ml; range 95.5–547.7 pg/ml) groups, and were followed for the development of breast cancer." (PMID 32318347, 2020). "In summary, 1,25(OH)2D may protect against breast cancer by activating its receptor and inactivating the CTSL-mediated degradation of TP53BP1 in A-type lamin-deficient cells, which display BRCA1 deficiency, including cells with lost BRCA1." (PMID 32456160, 2020). "All 37 BRCA1/2 WT cases with 38 P or LP variants (35 SNVs/indels and 3 CNVs) had strong family history (HBOC history level 1 or 2), and data were available regarding primary tumor site (breast or ovary), age at primary tumor diagnosis, breast cancer laterality, and other cancer type 13." (PMID 32566746, 2020). "Since p38α inhibition increases DNA damage and chromosome instability in breast cancer and THZ1-regulated DNA homologous recombination repair associated genes such as BRCA1 and BRCA2, the role of DNA damage in antitumor effects of THZ1 may need further exploration." (PMID 32690037, 2020). "AMH may however be reduced at the time of diagnosis in some conditions, including lymphoma, but probably not in women with breast cancer unless they are carriers of BRCA1 mutations." (PMID 33117288, 2020). "It is plausible that oophorectomy may reduce breast cancer risk in BRCA2 mutation carriers but not in BRCA1 mutation carriers." (PMID 31948486, 2020). "Furthermore, although the splicing vector pSAD was initially developed to study the breast cancer genes BRCA1 and BRCA2, it has also been demonstrated to be a powerful tool to test other disease genes such as SERPINA1, CHD7, and UGT1A1, as well as others currently under investigation." (PMID 32211025, 2020). "While BRCA1/2 related hereditary tumors may not have a unique phenotype, the breast cancers that carry BRCA1/2 deficiency have a unique genotype characterized by distinctive mutation profile." (PMID 32164626, 2020). "In this study, upregulated inflammasome activation enriches TAMs' recruitment to suppress CD8+ T cell activation in Brca1 mutant mammary tumors; thus, inhibition of inflammasome activation could postpone tumor relapse and block lung metastasis after surgically removing primary cancers." (PMID 32195105, 2020).
breast cancer (continued). "In the reviewed population, the genetic background of breast cancer patients has not been defined; therefore, it is not possible to figure out whether radiosensitivity assays are able to screen the BRCA1-2 mutation carrier for radiotherapy complications." (PMID 33013205, 2020). "Promoter hypermethylation is a well-known mechanism of transcriptional repression of tumor suppressor genes in breast cancer, including BRCA1, APC, CDH1, FANCF, among others, and may provide a complementary pathway of molecular carcinogenesis, independent of mutations." (PMID 33227964, 2020). "Furthermore, BRCA1 promoter hypermethylation has been shown to be a common early event in the development of TNBC, and epigenetic silencing of RAD51C, which is also strongly associated with signature 3 in basal-like breast cancer." (PMID 33227964, 2020). "Since PRMT1-dependent methylation of BRCA1 contributes to the epigenetic defense of breast cancer cells to IR (and probably to other DNA damage agents), these could explain, at least in part, why PRMT1 has been identified as a marker of unfavorable prognosis for breast cancer patients." (PMID 32764667, 2020). "However, certain PARPi in pre-clinical studies have been shown to inhibit cell growth and promote the death of breast cancer cells lacking mutations in BRCA1/2." (PMID 32235451, 2020). "The L-PCR model uncovered evidence for the utility of MRI texture features in distinguishing between BRCA1/2 positive and negative high-risk breast cancer individuals, which may suggest value to diagnostic routine." (PMID 32727387, 2020). "In addition, six BRCA1 variants were VUS; four of them were missense variants, one VUS was synonymous, and another was a new splice site change (c.5396-6 T > C) that was present for the first time in our breast cancer patient." (PMID 33067490, 2020). "However, in apparent contrast with these findings, it was observed that PKM2 deletion accelerates tumor formation in a BRCA1-deficient breast cancer mouse model, suggesting that PKM2 is not necessary for tumor cell proliferation." (PMID 33008042, 2020). "Outside of BRCA1/2 pathogenic variants, there is to date no validated screening test to identify breast cancer patients who may derive the most benefit from PARPi." (PMID 32235500, 2020). "Other frequently mutated genes in breast cancer, including Brca1 and Brca2, are not mutated." (PMID 32793490, 2020). "Besides, we identified H4K16ac and BRCA1 as new prime targets of SIRT4 in breast cancer." (PMID 32863939, 2020). "The data suggest that TMEM97 may be related to BRCA1 function in breast cancer cells." (PMID 32668577, 2020). "Therefore, we and others have proposed that the monoclonal antibody Denosumab (which specifically inhibits RANK/RANKL interactions) could potentially be used for the prophylactic treatment of breast cancer in BRCA1/2 carriers." (PMID 32850393, 2020). "Interestingly, we identified BRCA1 c.5096G>A in one woman with breast cancer and BRCA1 c.5407-25T>A in two women with breast cancer in our previous DNA-BONus study, where all women with newly diagnosed breast or ovarian cancer were offered BRCA genetic testing, regardless of family history or age." (PMID 32203205, 2020).
breast cancer (continued). "It has also been postulated that any observed association may be due to the use of tamoxifen for the prevention and treatment of breast cancer rather than a consequence of a BRCA1 or BRCA2 pathogenic variant per se." (PMID 32698099, 2020). "Furthermore, other studies have reported pathogenic mutations in BRCA1 in women without a family history of breast cancer and pathogenic mutations in SCN5A or KCNH2 in patients without phenotypic and electrophysiological evidence of cardiac arrhythmias." (PMID 32272925, 2020). "Not surprisingly, different mutations in BRCA1/2 cause variant subtypes of breast cancers." (PMID 32300589, 2020). "However, unlike in breast cancer studies, the status of BRCA1/2 mutations in our study was unrelated to CRS." (PMID 32131779, 2020). "Therefore, maybe there are functional connections between BRCA1, PPARγ and PFKP in glycolysis system and PFKP inhibitor may have a potential effect on BRCA1 dysfunctional breast cancer patients who suffer from diabetes and need treatments with PPARγ agonists." (PMID 32470015, 2020). "BRCA1 and BRCA2 are cancer predisposition genes that are inactivated in ~25% of inherited breast cancers, ~15% of all ovarian cancers and several other cancers, suggesting that PARP inhibitors might have potential in treating a wide-range of patients with BRCA-deficient tumours." (PMID 32183301, 2020). "BRCA1/2-associated breast cancer differs from cancer that arises in non-carriers." (PMID 32719921, 2020). "Moreover, common HMMR variants modify the risk of developing breast cancer for carriers of BRCA1, but not BRCA2, mutations." (PMID 32231069, 2020). "BRCA1 and BRCA2 mutations have also been reported in CVDs, for example, mutations in BRCA1 and BRCA2 are shown to be associated with a two‐fold increased risk for diabetes and a 37% increase of all‐cause mortality risk for breast cancer patients mainly due to CVDs (Zhou, Zhang, Gu, & Xia, 2015)." (PMID 32638521, 2020). "Since more than 90% of breast cancer cases do not have a mutation in the encoding sequence of BRCA1 protein, it is proposed that downregulation of the BRCA1 gene expression may be one of the major causes of nonfamilial sporadic breast cancer." (PMID 31963223, 2020). "The latest reports show though that deleterious BARD1 variants may be the reason for hereditary breast cancer in BRCA1 and BRCA2 negative families." (PMID 33114377, 2020). "Given that aberrantly lower levels of circulating RANKL have previously been described among women with a BRCA mutation, along with the important role of RANK signaling in BRCA1-breast cancer development, it is necessary to evaluate whether levels of circulating RANKL also predict cancer risk." (PMID 31069010, 2019). "Thus, BRCA1 or BRCA2 deficiency could lead to serious mistakes in the DNA repair process, which results in breast cancer." (PMID 30890936, 2019). "As such, it might be expected that women who volunteer for the KTB are more likely to have a positive family history of breast cancer, and this was noted for 26.7% of our study population, although women with BRCA1/2 positivity were excluded from our study cohort." (PMID 31687025, 2019). "BRCA1 basal-like breast cancers may originate from basal stem cells." (PMID 31555586, 2019). "Interestingly, no changes in total protein levels were found in breast cancer patients with the BRCA1 mutation." (PMID 31597313, 2019). "Moreover, mutations in BRCA1 and BRCA2 genes affect both hereditary and sporadic breast cancers." (PMID 30909550, 2019).
breast cancer (continued). "Thus, we evaluated the association between reproductive, hormonal, and lifestyle risk factors and mammographic density among women with a strong family history of breast cancer but no BRCA1 or BRCA2 mutation." (PMID 31242899, 2019). "Breast cancer patients with BRCA1/2‐driven tumors may benefit from targeted therapy." (PMID 30175445, 2019). "In addition, a study using a breast cancer cell line showed that high intracellular levels of Akt repressed nuclear translocation of breast cancer susceptibility 1 (BRCA1) and Rad51, resulting in the lack of homologous recombination of DNA DSB repair." (PMID 30521029, 2019). "Therefore, it is conceivable that PTEN loss, such as that mediated by inactivating PTEN gene mutation, may be one mechanism underlying the differences in immunophenotype between BRCA1- and BRCA2-deficient breast cancers." (PMID 31022191, 2019). "BRCA1- and BRCA2-deficient breast cancers were shown to be associated with elevated proportion of signature 3, suggesting an underlying deficiency in homologous recombination repair, and by extension, higher degree of genomic instability in these groups of breast cancers." (PMID 31022191, 2019). "Indeed, susceptibility variants have been found to modify the risk of breast cancer development associated with the BRCA1 and BRCA2 mutations, thereby accounting for the variation in breast cancer penetrance observed for these mutations in different human families." (PMID 30901340, 2019). "None of the breast cancer risk factors examined differed between BRCA1 and BRCA2 carriers." (PMID 30175445, 2019). "However, analyzing individuals wild-type for BRCA1/2 germline mutations, Hansmann and colleages identified WBC BRCA1 methylation in 3 out of 39 patients with ovarian cancer (8%) and belonging to families with an elevated risk of ovarian and breast cancer." (PMID 31225507, 2019). "Second primary breast cancers are more frequent in carriers of BRCA1/BRCA2 mutations and this higher frequency drives early genetic testing to inform surgical decision-making, even though recent studies have questioned the role of BRCA1/BRCA2 mutations in breast cancer survival." (PMID 31491032, 2019). "BRCA1 expression modified the effect of T cell activation status on patient survival in breast cancer, suggesting that the existence of neoantigens and the enhancement of neoantigen presentation in combination with immune checkpoint blockade may have synergistic effects on patient outcome." (PMID 31023256, 2019). "Furthermore, there is strong data demonstrating that the use of estrogen alone after RRBSO does not increase the risk of breast cancer among women with a BRCA1 mutation." (PMID 31362334, 2019). "Somatic mutations in BRCA1 and BRCA2 mutations may also arise in sporadic cases of breast cancer." (PMID 31022191, 2019). "Our study did not observe an association between haplogroup T1a1 and breast cancer risk, which may be attributed to differences in our population-based study population in comparison to BRCA1/2 carriers and differences in study power." (PMID 31577800, 2019). "In addition, epigenetic and genetic alterations in key breast cancer genes such as BRCA-1/2 and their downstream regulation of DNA repair mechanisms, or in genes with impact on epithelial cell proliferation, differentiation and migration are suggested to promote breast cancer carcinogenesis." (PMID 31203442, 2019). "The contribution of BRCA1/2 mutations to familial breast cancer in Bahrain has not been explored." (PMID 31131559, 2019). "In light of the increased clinical efforts to use SAHA and other HDAC inhibitors for breast cancer therapy, our data suggest that both the BRCA1 status and the hypoxic tumor microenvironment are potential important parameters that may affect the clinical efficacy of HDAC inhibitors." (PMID 31273285, 2019).